PXT1 (peroxisomal testis enriched protein 1)
Synonyms: STEPP
Tractability: No criterion of Open Targets' tractability assessment is met for any kind of drug.
Gene: Protein-coding gene on chromosome 6 (36,390,551 to 36,442,854, reverse strand). Ensembl gene ENSG00000179165.
Subcellular location: Peroxisome
Subcellular location (Human Protein Atlas): Vesicles
Gene Ontology:
Molecular function: protein binding
Cellular component: peroxisome
Genetic constraint (gnomAD): Loss-of-function variants: 5 observed, 7.66 expected, observed/expected ratio (o/e) 0.65, 90% interval 0.34 to 1.36. That is too few expected variants to judge how well the gene tolerates losing a copy. Missense variants: 110 observed, 120.38 expected, observed/expected ratio (o/e) 0.91, 90% interval 0.78 to 1.07. Synonymous variants: 35 observed, 40.19 expected, observed/expected ratio (o/e) 0.87, 90% interval 0.66 to 1.15.
Homologues: Orthologues: chimpanzee PXT1 (98% identical), dog PXT1 (78% identical), pig PXT1 (75% identical), mouse Pxt1 (37% identical), rat Pxt1 (34% identical).
Diseases named in the same sentence as PXT1 in open-access papers:
PXT1 is named in the same sentence as 2 diseases in open-access papers, as found by Europe PMC text mining. Sharing a sentence is not in itself a finding about the gene and the disease. The quoted sentences say what the papers report.
Infertility (1 paper, 2022). "Interestingly, PXT1 encodes a male germ cell-specific peroxisomal protein that could induce germ cell apoptosis and leads to infertility in male mice." (PMID 35672318, 2022).
PXT1 also shares sentences with these, for which no sentence is quoted: tumour (1 paper).